PF4 (platelet factor 4)
Diseases named in the same sentence as PF4 in open-access papers (continued):
Sharing a sentence is not in itself a finding about the gene and the disease.
inflammatory bowel disease (5 papers, 2017 to 2025). A spectrum of small and large bowel inflammatory diseases of unknown etiology. "Others studies suggested that serum PF4 plays an important role as a potential biomarker of human chronic diseases, in particular inflammatory bowel disease." (PMID 31374089, 2019). "PF4 is released from activated platelets, acts to facilitate blood clotting and plays a key pro-inflammatory role in inflammatory bowel disease and NEC." (PMID 28830381, 2017).
intracerebral hemorrhage (5 papers, 2021 to 2025). A cerebrovascular disorder characterized by bleeding into one or both cerebral hemispheres including the basal ganglia and the cerebral cortex. "Moreover, an extensive intracerebral hemorrhage and positivity for the anti-PF4 test were reported." (PMID 34945172, 2021).
leukemia (5 papers, 2013 to 2024). A malignant (clonal) hematologic disorder, involving hematopoietic stem cells and characterized by the presence of primitive or atypical myeloid or lymphoid cells in the bone marrow and the blood. "We further injected 10,000 B-ALL cells together with 2 × 105 total BM cells into lethally irradiated recipients, including Cdh5-Cre;Vps33bfl/fl, Prx1-Cre;Vps33bfl/fl and Pf4-Cre;Vps33bfl/fl mice, and monitored the effects on leukemia development." (PMID 37751067, 2024). "Levels of isoform 1 of fibrinogen alpha chain precursor protein and PF4 protein were both decreased in leukemia cells comparing with normal cells." (PMID 23915341, 2013). "Importantly, some of these genes have already been reported in relation to CML (e.g., AURKB, AZU1, HLA-B, HLA-DMB, PF4) and others have been found to play important roles in different leukemias (e.g., CDCA3, RPL18A, PRG3, TLX3)." (PMID 35008420, 2022).
lung adenocarcinoma (5 papers, 2023 to 2025). A carcinoma that arises from the lung and is characterized by the presence of malignant glandular epithelial cells. "PF4, as a chemokine, induces megakaryopoiesis in a mouse model of lung adenocarcinoma." (PMID 40512151, 2025). "Notably, Ppbp and Pf4, as key genes, play important roles in the prognosis and pathogenesis in lung adenocarcinoma (LUAD)." (PMID 38622609, 2024).
monoclonal gammopathy (5 papers, 2025 to 2026). A condition characterized by the abnormal presence of monoclonal immunoglobulins in the blood or urine. "An underlying monoclonal gammopathy with a paraprotein exposing anti-PF4 antibody-like features has been proven to activate platelets and cause recurrent thromboses in different patients." (PMID 40236285, 2025). "•Chronic anti-PF4 disorders could be linked with monoclonal gammopathy of thrombotic significance." (PMID 40236285, 2025). "Recently, a thrombotic thrombocytopenic disorder was observed in 9 patients with monoclonal gammopathy of undetermined significance (MGUS), associated with platelet-activating monoclonal anti-platelet factor 4 (PF4) antibodies." (PMID 40573981, 2025). "In addition to anti-PF4 antibody screening, protein electrophoresis and immunofixation should be performed to reveal monoclonal gammopathy." (PMID 40236285, 2025). "In patients whose chronic anti-PF4 thrombosis is caused by a paraprotein, meaning their MGUS has developed into an monoclonal gammopathy of thrombotic significance (MGTS), it may even be necessary to start antimyeloma therapy." (PMID 40236285, 2025). "These disorders include various acute and chronic VITT-like conditions, i.e. post-viral VITT, diaplacentally transmitted anti-PF4 antibodies in neonatal stroke, monoclonal gammopathies of thrombotic significance (MGTS) and chronic autoimmune VITT of unknown origin." (PMID 41646984, 2026).
thrombotic thrombocytopenic purpura (5 papers, 2022 to 2025). "In 2020, PF4–VWF complexes were first found in patients with thrombotic thrombocytopenic purpura (TTP)." (PMID 36926331, 2023). "We also investigated anti-PF4 Ig as autoantibody markers of the thrombotic thrombocytopenic purpura that has been recently described after the adenovirus-based anti–SARS-CoV-2 vaccine." (PMID 35911726, 2022).
vasculitis (5 papers, 2021 to 2025). "This case report describes a patient with antineutrophil cytoplasmic antibody (ANCA)-associated vasculitis (AAV) who, while under immunosuppression, developed anti-PF4-mediated immunothrombosis, with NETosis significantly elevated compared to baseline markers observed during AAV." (PMID 40276517, 2025). "Finally, an 86-year-old woman with anti-PF4 mediated immune thrombosis, occurring in the absence of prior heparin exposure, associated with crescentic glomerulonephritis secondary to perinuclear anti-neutrophil cytoplasmic antibody (p-ANCA)-associated vasculitis, was reported." (PMID 40573981, 2025).
anemia (4 papers, 2023 to 2025). A reduction in the number of red blood cells, the amount of hemoglobin, and/or the volume of packed red blood cells. "Anti-PF4/P antibodies have not been described in association with anemia, but we observed an inverse correlation in patients with UM between anti-PF4/P and HgB (Rs = –0.225, P = 0.015) and packed cell volume (PCV) (Rs = –0.200, P = 0.029)." (PMID 38652559, 2024). "Similar to anti–PF4/P IgG, we also observed a negative correlation between CICs and markers of anemia (PCV: Rs = –0.256, P = 0.040; HgB: Rs = –0.313, P = 0.01) in patients with UM." (PMID 38652559, 2024). "In addition, PF4 Cre iDTR mice exhibited anemia; however, red blood cells are not expected to be directly affected by DT treatments, as they do not express the DT receptor." (PMID 37830633, 2023).
Arthritis (4 papers, 2011 to 2021). Inflammation of a joint. "PF4 plasma levels were increased in all PG-PS-induced arthritis animals when compared to untreated and clopidogrel-treated animals." (PMID 22028806, 2011).
atopic dermatitis (4 papers, 2015 to 2023). "The level of molecules correlated with the plasma concentration of platelet factor 4 (PF-4) and the plasma concentration of thymus-and-activation-regulated chemokine (TARC), which, as with miR-223, may indicate the role of platelet activation in the pathogenesis of atopic dermatitis." (PMID 37298095, 2023).
bacterial sepsis (4 papers, 2016 to 2025). "In bacterial sepsis, PF4 binds to glycosaminoglycans (GAGs) on the surface of aerobic bacteria, giving rise to an antigenic complex that induces the early formation of anti-PF4 IgG-IgA-IgM." (PMID 32846949, 2020). "In conclusion, we demonstrated that, in the course of bacterial sepsis, platelet activation leads to the formation of specific PF4-bearing PMPs." (PMID 32846949, 2020). "This patient developed MSSA bacteremia, and it was possible that he experienced an abnormal immune response to the complex of bacteria and PF4 and produced anti-heparin/PF4 antibodies due to enhanced SLE activity." (PMID 27699076, 2016).
Hypercholesterolemia (4 papers, 2018 to 2024). An increased concentration of cholesterol in the blood. "While hypercholesterolemia has been previously associated with platelet activation, we found that patients have both increased circulating levels of sP-selectin and PF-4/CXCL4, which are involved in multiple atherogenic processes." (PMID 30583563, 2018). "The results showed that high-fat diet-induced hypercholesterolemia and hypertriglyceridemia significantly increased the plasma levels of β-thromboglobulin (β-TG), p-selectin, and platelet factor 4 (PF-4)." (PMID 37892538, 2023). "The plasma levels of β-TG, p-selectin, PF-4, and TxA2 were analyzed using ELISA to investigate platelet reactivity in our hypercholesterolemia/hypertriglyceridemia rat model." (PMID 37892538, 2023).
hyperlipidemia (4 papers, 2017 to 2024). "The resident cluster expressed the pro-atherogenic chemokine Pf4, suggesting a role in cell activation to hyperlipidemia, attracting immune cells." (PMID 35419441, 2022).
ischemia (4 papers, 2021 to 2024). A hypoperfusion of the BLOOD through an organ or tissue caused by a PATHOLOGIC CONSTRICTION or obstruction of its BLOOD VESSELS, or an absence of BLOOD CIRCULATION. "On the other hand, platelets modulate leukocyte function but also contribute to tissue injury caused by ischemia by producing proinflammatory mediators, such as platelet factor-4, leukotriene, thromboxane, platelet-derived growth factor, and serotonin." (PMID 38255192, 2023). "Comparing ischemic hindlimb muscles from platelet-specific C5aR1-deficient mice with Pf4-cre−C5ar1fl/fl control mice at day 14 after induction of ischemia, we observed increased pericyte density and enhanced pericyte coverage in platelet-specific C5aR1-deficient mice." (PMID 34099640, 2021). "However, after 24 h of reperfusion, we detected a reduced infarct size in FasLfl/fl-Pf4-Cre+ mice compared to controls due to reduced cell apoptosis after ischemia and reperfusion injury." (PMID 38791039, 2024).
liposarcoma (4 papers, 2012 to 2025). A usually painless malignant tumor that arises from adipose tissue. "Using mass spectrometry and immunoassays with anti-PF-4 antibody, they were able to show upregulation of PF-4 in early growth of liposarcoma and osteosarcoma." (PMID 40526331, 2025). "This study should be followed by the functional assessment of PF-4 levels in platelets of patients with liposarcoma and extensive validation of clinical materials." (PMID 22778956, 2012). "Also, CXCL4/PF-4 has been proposed as a biomarker of early tumor growth in different tumors types, and appears to be up-regulated in human liposarcoma, mammary adenocarcinoma, osteosarcoma and in other hematologic disorders." (PMID 25298751, 2014). "Increase in PF-4 levels in platelets was observed in both angiogenic and nonangiogenic xenografts of liposarcoma, whereas it was upregulated only in angiogenic xenografts of breast cancer and osteosarcoma." (PMID 22778956, 2012).
myocardial ischemia (4 papers, 2018 to 2022). A disorder of cardiac function caused by insufficient blood flow to the muscle tissue of the heart. "PF4 is induced by atherosclerotic lesions and myocardial ischemia, while serpin E1 release is associated with impaired basal fibrinolytic activity." (PMID 35109843, 2022). "After we found enhanced platelet clot formation at ZT8 in Per2loxP/loxP-PF4-CRE, we next exposed Per2loxP/loxP-PF4-CRE and PF4-CRE controls to in-situ myocardial ischemia and reperfusion injury at ZT8." (PMID 33382840, 2020).
osteosarcoma (4 papers, 2014 to 2025). A usually aggressive malignant bone-forming mesenchymal neoplasm, predominantly affecting adolescents and young adults. "However, some clinical evidence suggest that plasma PF4 is elevated in a number of cancers including breast, prostate, colorectal, and osteosarcoma." (PMID 27223426, 2017).
periodontitis (4 papers, 2021 to 2024). An acute or chronic inflammatory process that affects the tissues that surround and support the teeth. "Platelet activation, and the attendant release of pro-inflammatory chemokines such as platelet factor 4 (CXCL4/PF4), are associated with periodontitis although the associated biochemical pathways remain undefined." (PMID 36329090, 2022).
pneumonia (4 papers, 2017 to 2025). An acute, acute and chronic, or chronic inflammation focally or diffusely affecting the lung parenchyma, caused by an infection in one or both of the lungs (by bacteria, viruses, fungi, or mycoplasma.). "In a murine acute pneumonia model, mice treated with Pf4 associated with OMVs show significantly less neutrophil infiltration in BAL fluid than mice treated with purified Pf4." (PMID 37965262, 2023).
preeclampsia (4 papers, 2012 to 2025). Preeclampsia is a hypertensive disorder of pregnancy that is characterized by new-onset hypertension with proteinuria presenting after 20 weeks of gestation, and depending on mild or severe forms may initially present with severe headache, visual disturbances, and hyperreflexia. "This is consistent with our microarray results showing for instance an increased expression of Cxcl10, which similarly to PF4 exerts a potent pro-inflammatory and anti-angiogenic action that has been involved in the pathophysiology of preeclampsia." (PMID 23056436, 2012). "Several markers of platelet activation, such as P-selectin, platelet factor 4 (PF4) and Annexin-V, have been investigated in preeclampsia." (PMID 40490753, 2025). "Procoagulant platelet factors are increased in patients with preeclampsia, such as plasma levels of transforming growth factor-β (TGF-β) and platelet factor-4 (PF4 or CXCL4)." (PMID 35455936, 2022). "To characterize other pathways involved in the regulation of decidual angiogenesis we next focused on platelet factor 4 (PF4), an ELR-negative chemokine that exhibits anti-angiogenic properties and is up-regulated during the course of preeclampsia." (PMID 23056436, 2012).
psoriasis (4 papers, 2022 to 2023). An autoimmune condition characterized by red, well-delineated plaques with silvery scales that are usually on the extensor surfaces and scalp. "In conclusion, PF4 is a proper marker of platelet activation associated with psoriasis and CVD, and elevated levels of PF4 suggests the essential role of platelet activation in these diseases, which still needs to be studied in depth." (PMID 37654493, 2023). "Platelet factor 4 (PF4) and β-thromboglobulin (β-TG), the most abundant CXC chemokines of platelet α-granules, were found increased in human psoriasis and associated with PASI scores." (PMID 35213665, 2022). "Significant higher PF4 levels were found in psoriasis patients when compared with healthy controls." (PMID 37654493, 2023).
renal fibrosis (4 papers, 2018 to 2025). A final common manifestation of a wide variety of chronic kidney diseases characterized by glomerulosclerosis and tubulointerstitial fibrosis. "The results of intercellular interactions between macrophages and fibroblasts suggest a direct involvement of PF4+ macrophages in renal fibrosis." (PMID 38167034, 2024). "Additionally, PF4+ macrophages were identified as key players in promoting renal fibrosis and a pro-tumorigenic microenvironment." (PMID 39217203, 2025). "Furthermore, the pronounced upregulation of α-SMA with the increase of PF4+ macrophage content provided compelling evidence of the potential involvement of PF4+ macrophages in renal fibrosis induction, consistent with previous reports." (PMID 38167034, 2024). "Finally, this research employs scRNA-seq technology to identify a PF4+ macrophage subset and provide insights into its potential role in promoting renal fibrosis after PS-MPs plus HFD exposure, in accordance with a previous study linking PF4+ macrophages to renal fibrosis." (PMID 38167034, 2024). "Interestingly, the results indicated PS-MPs plus HFD treatment enhanced cell-to-cell communication between MPs and fibroblasts, suggesting that PF4+ macrophages may contribute to renal fibrosis by directly interacting with fibroblasts." (PMID 38167034, 2024).
acute myeloid leukemia (3 papers, 2013 to 2022). Acute myeloid leukemia (AML) is a group of neoplasms arising from precursor cells committed to the myeloid cell-line differentiation. "VEGF is reported to be repressed by RUNX1 in acute myeloid leukemia, whereas PF4 (platelet factor 4) is upregulated by RUNX1 in human erythroleukemia cells." (PMID 29050333, 2017). "Kim’s group found that PF4 protein levels were a good indicator for the recovery of blood count in the complete remission of acute myeloid leukemia." (PMID 23915341, 2013). "Further, an in-depth literature analysis revealed that several of these genes play important roles in cancer (CDCA3, ECEL1, EN1, HLA-DMB, SPRR2A, TMEM40) including acute myeloid leukemia (CDCA3, HLA-DMB, RPL18A, PF4, PRG3) and T cell acute lymphoblastic leukemia (TLX3)." (PMID 35008420, 2022).
Alzheimer disease (3 papers, 2025). A progressive, neurodegenerative disease characterized by loss of function and death of nerve cells in several areas of the brain leading to loss of cognitive function such as memory and language. "Clinically, reduced serum PF4 levels have been significantly associated with cognitive decline and core pathological biomarkers in Alzheimer’s disease." (PMID 40193115, 2025).
endometritis (3 papers, 2022 to 2023). An acute or chronic, usually bacterial infectious process affecting the endometrium. "Specific mRNA expression patterns of C3, C2, LTF, PF4, and TRAPPC13 are present in the blood and endometrium of dairy calves with subclinical endometritis." (PMID 37756095, 2023). "Additionally, C3, C2, LTF, PF4, and TRAPPC13 had unique mRNA expression patterns in the blood and endometrial tissue of dairy cows with subclinical endometritis." (PMID 37368756, 2023). "A total of 14 predicted upstream regulators were identified only in healthy cows (P < 0.05), while five unique predicted upstream regulators were identified only in cows after uterine infection, including the inhibition of ISG15 and AIRE, and activation of DUSP1, NFKBIA, and PF4 (P < 0.05)." (PMID 35358206, 2022).
Hypofibrinogenemia (3 papers, 2022 to 2025). Decreased concentration of fibrinogen in the blood. "Furthermore plasma exchange (PLEX), preferably against plasma rather than albumin, could represent an alternative option for reducing the amount of circulating PF4/vaccine complexes and correcting hypofibrinogenemia." (PMID 35821156, 2022).
influenza (3 papers, 2018). An acute viral infection of the respiratory tract, occurring in isolated cases, in epidemics, or in pandemics; it is caused by serologically different strains of viruses (influenzaviruses) designated A, B, and C, has a 3-day incubation period, and usually lasts for 3 to 10 days. "Recently, platelet factor 4 (PF4/CXCL4), a chemokine secreted exclusively by platelets and megakaryocytes, was identified as an essential mediator for neutrophil recruitment and virus clearance in influenza A infection (also see Platelet Activation in Influenza)." (PMID 29761104, 2018).
lymphedema (3 papers, 2022 to 2024). Excess fluid collection in tissues, causing swelling. "Elevated platelet factor 4 (PF4), an inflammatory cytokine that also promotes blood coagulation, was found in blood-borne exosomes of patients with lymphedema and other lymphatic conditions." (PMID 35743063, 2022).